HP (haptoglobin)
Diseases named in the same sentence as HP in open-access papers (continued):
Sharing a sentence is not in itself a finding about the gene and the disease.
osteoporosis (2 papers, 2016 to 2019). A condition of reduced bone mass, with decreased cortical thickness and a decrease in the number and size of the trabeculae of cancellous bone (but normal chemical composition), resulting in increased fracture incidence. "This was linked to a variation in the haptoglobin molecule which binds heme more avidly and reduces the amount of free iron available to tissues and which protected against fracture in postmenopausal women with osteoporosis." (PMID 27123357, 2016). "The succinyl‐proteome experimental data indicated that apolipoprotein A‐I, apolipoprotein A‐II, hemoglobin subunit alpha, and haptoglobin were valuable for diagnosis and treatment in postmenopausal women with osteoporosis and osteopenia." (PMID 31663278, 2019).
paroxysmal nocturnal haemoglobinuria (2 papers, 2015 to 2025). "Administration of haptoglobin infusions is shown to attenuate cell-free haemoglobin-mediated AKI in paroxysmal nocturnal haemoglobinuria and an experimental model of stored blood transfusion." (PMID 26081927, 2015).
Pyoderma (2 papers, 2020 to 2024). Any manifestation of a skin disease associated with the production of pus. "Dogs’ pyoderma treated with A. vera gel ointment had low haptoglobin and tumor necrosis factor-α concentrations than gentamicin." (PMID 38667017, 2024). "Dogs’ pyoderma treated with A. vera gel ointment 20% and 40% were more likely to have low haptoglobin and tumor necrosis factor-α concentrations than gentamicin 1% ([odds ratio [OR]=4.6; 95% confidence interval [CI]=1.31-17.40; p<0.05]; [OR=5.2; 95% CI=1.04-22.30; p<0.05]), respectively." (PMID 33363329, 2020).
Salmonella Infections (2 papers, 2012 to 2022). Infections with bacteria of the genus SALMONELLA. "Furthermore, in patients, serum HP levels increase during complement activation associated with Salmonella infection, and HP KO mice exhibit a reduced ability to control the infection." (PMID 36497163, 2022). "In the HP group, only 16.7% of mice (1 out of 6 mice) tested positive for Salmonella infection, with an average of 3 × 103 cfu/g; however, no p HP plasmid could be isolated." (PMID 23013063, 2012).
sarcopenia (2 papers, 2024 to 2025). Progressive decline in muscle mass due to aging which results in decreased functional capacity of muscles. "Our MR studies suggest that increasing the abundance of HP protein may reduce the risk of sarcopenia." (PMID 38644354, 2024). "Drug repurposing analysis supported zinc supplementation and collagenase clostridium histolyticum might be potential therapeutics for sarcopenia by activating HP and inhibiting COL15A1, respectively." (PMID 38644354, 2024). "Upon evaluating the clinical development potential of these drug target genes, we found zinc supplementation and collagenase clostridium histolyticum might be potential therapeutics for sarcopenia by activating HP and inhibiting COL15A1, respectively." (PMID 38644354, 2024). "These two drugs might be potential therapeutics for sarcopenia by activating HP and inhibiting COL15A1, respectively." (PMID 38644354, 2024). "The abundance of HP protein (per 1 SD increase) was associated with higher ALM (beta: 0.012, 95% CI: 0.007–0.018, P = 1.2*10−5) and higher grip strength (OR: 0.96, 95% CI: 0.94–0.98, P = 4.2*10−5), indicating the reduced risk of sarcopenia." (PMID 38644354, 2024). "Based on these integrated datasets, our study provides potential evidence for the genetic colocalization of six drug target genes (HP, HLA‐DRA, MAP 3K3, MFGE8, COL15A1, and AURKA) with sarcopenia." (PMID 38644354, 2024). "The results revealed that six potential druggable genes (HP, HLA‐DRA, MAP 3K3, MFGE8, COL15A1, and AURKA) passed the colocalization analysis and were present in more than one QTL datasets or sarcopenia‐related traits." (PMID 38644354, 2024). "Our research indicated MAP 3K3, MFGE8, COL15A1, HP, and HLA‐DRA may serve as promising targets for sarcopenia, while the effectiveness of zinc supplementation and collagenase clostridium histolyticum for sarcopenia requires further validation." (PMID 38644354, 2024).
squamous cell carcinoma (2 papers, 2012 to 2023). A carcinoma arising from squamous epithelial cells. "The associations for haptoglobin and sedimentation rate were observed for both squamous cell carcinoma and adenocarcinoma." (PMID 37876941, 2023).
Ss (2 papers, 2014 to 2020). "To determine the effect of Ss infection on systemic inflammation in T2DM, we measured the levels of acute phase proteins (α-2M, CRP, haptoglobin and SAA-1) in Ss+ and Ss− individuals." (PMID 32984066, 2020). "Active TB in the presence of Ss infection exhibited significantly higher levels of α-2m, CRP, SAA and haptoglobin in comparison to NTB individuals with Ss infection." (PMID 25375117, 2014).
staphylococcus aureus infection (2 papers, 2013 to 2022). An infectious process in which the bacteria Staphylococcus aureus is present. "The current study showed that cathelicidin-1 and haptoglobin were related to Staphylococcus aureus infection." (PMID 35479637, 2022). "Cathelicidin-1 and haptoglobin might be involved in Staphylococcus aureus infection (corrected p = 0.037)." (PMID 35479637, 2022). "Also looking at the liver response, experimental Staphylococcus aureus infection resulted in an approximate 4 fold reduction in ORM1 expression at 30–48 hours after challenge, concomitantly with a pigMAP gene induction of around 20 fold and a haptoglobin gene expression fold change around two." (PMID 23844161, 2013).
systemic vasculitis (2 papers, 2011 to 2018). "Haptoglobin also has a role in stimulating angiogenesis and has been identified as an angiogenic factor in sera from patients with systemic vasculitis." (PMID 21385403, 2011).
Thrombocytosis (2 papers, 2016 to 2020). Increased numbers of platelets in the peripheral blood. "Haptoglobin concentration was above the reference level in 18 patients (38 %), while thrombocytosis was present in 7 patients (13 %)." (PMID 27444431, 2016).
trachoma (2 papers, 2010 to 2015). "No SNP(PEMMAX < 0.01) was detected in any of thegenes IL8, IL10, CSF2, IFNG, HP, CCL8 or MMP9; all of which had beenpreviously reported to associate with trachoma." (PMID 26616738, 2015).
Trichinella spiralis infection (2 papers, 2011 to 2024). "Furthermore, a Th1 adjuvant of bacterial origin called Helicobacter pylori neutrophil activating protein (HP-NAP), administered during the intestinal phase of trichinellosis, alters the Th2 dependent response at muscle level." (PMID 21429196, 2011).
triple-negative breast carcinoma (2 papers, 2019 to 2022). An invasive breast carcinoma which is negative for expression of estrogen receptor (ER), progesterone receptor (PR), and human epidermal growth factor receptor 2 (HER2). "Recently, in a human triple-negative breast cancer xenograft model, dramatic up-regulation of plasma haptoglobin was observed after metastasis, suggesting the potential of HP as a biomarker for metastasis." (PMID 35818030, 2022). "A different study looking at the expression of haptoglobin in patients with triple negative breast cancer identified it to be a potential biomarker." (PMID 31042781, 2019). "Since this is in line with our results, it is thus tempting to suggest that haptoglobin is a possible specific biomarker for triple negative breast cancer." (PMID 31042781, 2019).
ventilator-associated pneumonia (2 papers, 2025). Serious INFLAMMATION of the LUNG in patients who required the use of PULMONARY VENTILATOR. "More recently, in a study involving ICU patients undergoing veno-venous extracorporeal membrane oxygenation (ECMO), haptoglobin levels were associated with vascular tone modulation, ventilator-associated pneumonia (VAP), and ICU mortality." (PMID 40429487, 2025). "Secondary aims included assessment of association between COHb and haptoglobin with the development of ventilator-associated pneumonia (VAP) and with hemodynamics." (PMID 39078479, 2025). "In a recent study by Rezoagly, low levels of haptoglobin accompanied by high carboxyhemoglobin levels were signs of an increased risk of incidence of secondary infections, such as ventilator-associated pneumonia, and higher ICU mortality in a population of ARDS patients on ECMO." (PMID 40429487, 2025).
vivax malaria (2 papers, 2012 to 2017). "Analysis of the longitudinal cohort of vivax malaria patients by ELISA indicated reversible alterations (compared to the normal serum levels) in the serum abundances of HP, ApoE and Apo A1 during the acute and remission phases of the infection." (PMID 28667326, 2017). "ROC curves indicate SAA, Apo A1 and HP are efficient predictor proteins (AUC > 0.80) for vivax malaria even at a low-parasitemic level." (PMID 28667326, 2017).
Wilson disease (2 papers, 2024). A very rare inherited multisystemic disease presenting non-specific neurological, hepatic, psychiatric or osseo-muscular manifestations due to excessive copper deposition in the body. "In addition, Coombs-negative hemolytic anemia is a key feature of Wilson disease with undetectable serum haptoglobin, high serum activities of lactate dehydrogenase, and high reticulocyte counts." (PMID 38731973, 2024). "In addition, Coombs-negative hemolytic anemia is a key feature of Wilson disease with undetectable serum haptoglobin." (PMID 38731973, 2024).
acute coronary syndrome (1 paper, 2020). Signs and symptoms related to acute ischemia of the myocardium secondary to coronary artery disease. "Thus, in our preliminary studies, we have identified 10 distinct altered phosphoproteins from CAD plasma, among which Apo-A1, hemopexin, haptoglobin, and Alpha-antitrypsin have been reported to be associated with acute coronary syndrome." (PMID 33299376, 2020).
acute lung injury (1 paper, 2009). A condition of lung damage that is characterized by bilateral pulmonary infiltrates (pulmonary edema) rich in neutrophils, and in the absence of clinical heart failure. "We have also previously reported that patients with acute lung injury (ALI) have changes in SP-A and acute phase proteins, such as haptoglobin and α1-AT." (PMID 19432985, 2009).
acute myeloid leukemia (1 paper, 2021). Acute myeloid leukemia (AML) is a group of neoplasms arising from precursor cells committed to the myeloid cell-line differentiation. "We describe here two GO-treated acute myeloid leukemia (AML) cases: both patients suffered from a toxic syndrome, which manifested as impaired hemoglobin-haptoglobin scavenging and accumulation of hemolysis-related products." (PMID 33824768, 2021).
acute pancreatitis (1 paper, 2024). An acute inflammatory process that leads to necrosis of the pancreatic parenchyma. "Only one animal experiment published in 2020 was detected, which showed an increase in haptoglobin levels observed during the acute phase of acute pancreatitis." (PMID 39364223, 2024). "However, there is relatively little research on haptoglobin in acute pancreatitis." (PMID 39364223, 2024).
adrenogenital disorder (1 paper, 2025). "On the other hand, we observed two significantly upregulated proteins in the urine proteome of patients with adrenogenital disorder: haptoglobin (HP) and F-actin capping protein subunit alpha-2 (CAPZA2)." (PMID 40425748, 2025).
adult-onset Still disease (1 paper, 2022). A rare inflammatory multisystem disorder characterized clinically by fever of unknown origin, arthralgia or arthritis, hyperleucocytosis, and typical skin rash. "However, it has been reported that haptoglobin level decreases in conditions such as adult-onset Still's disease and MIS-C, where inflammation is severe and haptoglobin precursor zonulin increases." (PMID 36158380, 2022).
allergic contact dermatitis (1 paper, 2020). An inflammatory skin condition caused by an immune response to direct contact between the skin and an allergen. "Different haptoglobin genotypes have been reported with higher risk of disease in humans including allergic contact dermatitis, bronchial asthma, and rhinitis." (PMID 32556497, 2020).
Allergy (1 paper, 2022). An allergy is an immune response or reaction to substances that are usually not harmful. "In this review, we discuss the immune modulating properties of the protein regarding the H. pylori infection and the evidence that support the potential clinical application of HP-NAP in allergy and cancer immunotherapy." (PMID 35844568, 2022).
anaphylaxis (1 paper, 2013). An acute hypersensitivity reaction that occurs from exposure to an allergen. "It is reported that patients who are genetically deficient in haptoglobin are at risk of anaphylaxis against blood components containing haptoglobin." (PMID 23555085, 2013).
anaplastic cancer (1 paper, 2012). "Very low expressions for haptoglobin, ferritin light chain, and ferritin heavy chain were found in both Riedel's thyroiditis and normal samples compared with those exhibiting anaplastic cancer, in which increases of more than 100, more than 500, and more than 300 were observed." (PMID 22480342, 2012).
aortic aneurysm (1 paper, 2025). A ruptured aneurysm located in the wall of the proximal portion of the descending aorta proceeding from the arch of the aorta. "We have reported an association between the status of enhanced-fibrinolytic-type DIC associated with aortic aneurysm, bleeding symptoms, factor XIII activity, and haptoglobin." (PMID 40725922, 2025). "In enhanced-fibrinolytic-type DIC due to aortic aneurysm, the microthrombi formed are lysed one after another by excessive fibrinolytic activation, so mechanical hemolysis is only mild and haptoglobin is considered mildly decreased to normal." (PMID 40725922, 2025).
appendicitis (1 paper, 2018). Acute inflammation of the vermiform appendix. "In agreement with our findings, the gene encoding the mediator haptoglobin was found overexpressed in the serum of appendicitis patients." (PMID 29529041, 2018).
asbestosis (1 paper, 2022). A lung disorder caused by inhalation of asbestos fibers. "Interestingly, asbestos exposure induces higher serum levels of haptoglobin, and a genetic polymorphism of haptoglobin, the phenotype Hp1-1, has been found more frequently in exposed individuals who developed asbestosis." (PMID 36362413, 2022).
atypical hemolytic-uremic syndrome (1 paper, 2025). A rare, genetic thrombotic microangiopathy due to dysregulation of the alternative complement pathway and characterized by the triad of hemolytic anemia, thrombocytopenia, and acute renal dysfunction. "Although a low haptoglobin level was historically included as one of the hemolytic anemia biomarkers in diseases such as atypical hemolytic uremic syndrome (aHUS), it is not uncommon to observe increased haptoglobin levels in TA-TMA diagnosis." (PMID 40406401, 2025).
bacterial pneumonia (1 paper, 2014). Acute infection of the lung parenchyma caused by bacteria (e.g., Streptococcus pneumoniae, Haemophilus influenzae, Chlamydia pneumoniae, Mycoplasma pneumoniae, and Legionella pneumophila). "Children with probable bacterial pneumonia presented with the highest concentrations of haptoglobin and Lpc-2." (PMID 24696240, 2014).
bone metastasis (1 paper, 2019). Transfer of a neoplasm from its primary site to bones. "Of these, CD59, haptoglobin, and tetranectin showed a significantly large fold change in patients with bone metastasis, which we further verified through immunohistochemistry and ELISA." (PMID 31413735, 2019).
brain injury (1 paper, 2024). Acute and chronic (see also brain INJURIES, CHRONIC) injuries to the brain, including the cerebral hemispheres, CEREBELLUM, and brain STEM. "Targeting haptoglobin pathways or enhancing its expression in the brain could therefore offer a promising approach to managing the effects of hemoglobin release and limiting secondary damage in brain injuries." (PMID 39765770, 2024).
bronchopneumonia (1 paper, 2009). Acute inflammation of the walls of the terminal bronchioles that spreads into the peribronchial alveoli and alveolar ducts. "Recently, it has been documented immunohistologically that in acute and chronic bronchopneumonia in pigs haptoglobin was found in airway epithelial cells and immigrated leukocytes but not in alveolar epithelial cells." (PMID 19383119, 2009).
brucellosis (1 paper, 2024). Brucellosis is a bacterial infection that spreads from animals to people via unpasteurized dairy products or by exposure to contaminated animal products or infected animals. "Haptoglobin and zinc have been identified as anti-inflammatory, immunomodulatory, and antioxidant modulators, which prevent oxidative tissue damage caused by acute brucellosis in seropositive animals." (PMID 39897353, 2024).
C. perfringens infection (1 paper, 2022). "The results may hint that HP was activated and involved in regulating the immune inflammatory response of piglet diarrhea, which may become a promising candidate marker for C. perfringens infection." (PMID 35402105, 2022). "To summarize, we first analyzed the comparative proteomics in piglets after of C. perfringens infection, and found that PPAR signaling pathway and haptoglobin may play an important role in C. perfringens infection." (PMID 35402105, 2022).
cerebral malaria (1 paper, 2024). A sequestration of Plasmodium falciparum in the brain, which can cause coma and/or seizures. "This is consistent with severe non-cerebral malaria being related with extensive hemolysis and accumulation of extracellular HB, presumably leading to HP depletion." (PMID 38307624, 2024).
cervical cancer (1 paper, 2023). A primary or metastatic malignant neoplasm involving the cervix. "In this study, given the importance of HP-PPIs and the potential differences between the HPV types most prevalent in cervical cancer (i.e., HPV16 and HPV18), a novel systems biology pipeline was used to develop efficient host-specific drug candidates against cervical cancer." (PMID 36761959, 2023).
chronic lower respiratory diseases (1 paper, 2020). "Moreover, protein haptoglobin, also included in GlycA signal, was estimated to be the strongest predictor of chronic lower respiratory diseases of all proteins included in this signal." (PMID 32677943, 2020).
chronic obstructive pulmonary disease (1 paper, 2018). A chronic and progressive lung disorder characterized by the loss of elasticity of the bronchial tree and the air sacs, destruction of the air sacs wall, thickening of the bronchial wall, and mucous accumulation in the bronchial tree. "Examples are alpha-1-antitrypsin for chronic obstructive pulmonary disease (COPD), haptoglobin for gastric cancer, and human chorionic gonadotrophin for ovarian and testicular tumors." (PMID 29497882, 2018).
co-infection (1 paper, 2013). "When patients with co-infection (HP+/EBV+) were compared against patients with no infection (HP−/EBV−) PR values for severe MN and PMN infiltration were undefined because none of the uninfected children (HP−/EBV−) had severe MN or PMN infiltration." (PMID 23638154, 2013).
Coats disease (1 paper, 2016). Coats disease (CD) is an idiopathic disorder characterized by retinal telangiectasia with deposition of intraretinal or subretinal exudates, potentially leading to retinal detachment and unilateral blindness. "Western blotting confirmed the expression levels of haptoglobin and apolipoprotein C-I were significantly up-regulated in Coats’ disease." (PMID 27416065, 2016).
cryptococcal infection (1 paper, 2025). "Herein, we show significant induction of haptoglobin within whole blood upon cryptococcal infection and propose its use as a diagnostic marker of disease." (PMID 41061967, 2025). "Finally, the direct connection between cryptococcal infection and haptoglobin induction observed within this study is a novel finding that correlates free iron and heme availability and scavenging through the recycling of hemoglobin, as well as macrophage activation upon infection." (PMID 41061967, 2025).